IL7 (interleukin 7)
Diseases named in the same sentence as IL7 in open-access papers (continued):
Sharing a sentence is not in itself a finding about the gene and the disease.
prostate carcinoma (continued). "In another model, TGFβ and IL-7 were included in a model predicting prostate cancer survival from 44 prostate cancer specimens." (PMID 22970379, 2012). "We evaluated IL-7 gene expression in CaP and normal prostate tissues, showing comparable IL-7 expression in prostate cancer and normal tissues." (PMID 18978943, 2008). "The analysis of the available data showed that NSCLC and prostate cancer had a statistically significant higher IL-7 serum levels compared to SCLC cases." (PMID 17205128, 2006). "The IL-7/IL-7R axis has been shown to activate NF-κB in prostate cancer cells." (PMID 40240976, 2025). "The IL-7/IL-7R axis contributes to prostate cancer cell migration via the PI3K-Akt pathway." (PMID 36672342, 2023). "Collectively, our in vivo results elucidated that NKG2D-based CAR T cells could effectively kill prostate cancer cells, and co-expression of IL-7 could enhance the antitumor function of NKG2D-CAR T cells against prostate cancer." (PMID 32698361, 2020). "Furthermore, transgenic expression of IL-7 enhanced the proliferative, persistence and anti-prostate cancer activity of NKG2D-CAR T cells in vitro and in vivo." (PMID 32698361, 2020). "Therefore, we suppose that NKG2D-CAR T cells expressing IL-7 would have the capacity to persist in the immuno-suppressive microenvironment in prostate cancer tissues and induce potent antitumor immunity in patients, but more evidence is needed." (PMID 32698361, 2020). "However, since we did not establish a proper orthotopic tumor model yet, we would like to evaluate the effect of IL-7 on prostate cancer in the future." (PMID 31061414, 2019). "Thus, the effect of IL-7 on the invasiveness of prostate cancer should be clarified through the orthotopic tumor model considering tumor microenvironment similar to that of the original tumor." (PMID 31061414, 2019). "We first explored whether prostate cancer cell line, PC-3, and its derivatives express IL-7 and IL-7Rα, and whether IL-7Rα expressed by these cells responds to IL-7." (PMID 31061414, 2019). "Interestingly, there was a statistically significant correlation between IL-7Rα and IL-7 expression in prostate cancer (r = 0.63, P < 0.001), suggesting that expression of the two molecules occurs simultaneously." (PMID 31061414, 2019). "The IL-7/IL-7R axis is related to cell invasion and migration, and blocking the IL-7/IL-7R axis may treat prostate cancer." (PMID 28486560, 2017). "But serum titers of IL-7 significantly increased in prostate cancer patients." (PMID 25955647, 2015). "Thus, in a multivariate model (which included TGFβ, IL-7, PSA, and Gleason Score) based on radical prostatectomy specimens, both TGFβ and IL-7 were independently predictive of prostate cancer survival, with hazard ratios of 10.4 and 0.1, respectively." (PMID 22970379, 2012). "Thus, we explored the mechanism through which IL-7 influences the invasiveness of prostate cancer, and whether the invasiveness induced by IL-7 can be controlled by inhibitors of this mechanism." (PMID 31061414, 2019). "The pro-metastatic growth factor interleukin-7 (IL-7) was shown to stimulate the AKT signaling, among other pathways, in prostate cancer cells." (PMID 34064589, 2021). "IL-7 is known to enhance the proliferation and survival of T cells, and co-expression of IL-7 improves NKG2D-based CAR T cells therapy on prostate cancer by enhancing the expansion, inhibiting cell apoptosis and exhaustion." (PMID 33292660, 2020). "During the early phase of metastasis, cytokines such as TGFβ, IL-6, CXCL8, IL-7, CXCL16, and CX3CL1 induce EMT in prostate cancer cells and transforms them to exhibit higher migratory and invasive potentials." (PMID 32585812, 2020). "This study showed that IL-7 enhances the migration and invasion of prostate cancer cells via EMT, suggesting that IL-7 and IL-7Rα are therapeutic targets for the treatment of prostate cancer." (PMID 31061414, 2019).
prostate carcinoma (continued). "In particular, gene expression data for prostate cancer patient samples showed that expression of EMT- and stem cell-related genes was prominent in cancer cells highly expressing both IL-7 and IL-7Rα." (PMID 31061414, 2019). "Meantime, IL‐7, IL‐8, and TNF‐α were significantly upregulated in patients with prostate cancer compared with patients with BPD and normal control subjects." (PMID 26880719, 2016). "IL-7 producing whole cell vaccine is also proved to evoke an effective anti-cancer immune response, probably mediated by NK1.1+ cells for subcutaneous prostate cancer challenge, while the GM-CSF producing vaccine is good at intraprostatic tumor challenge." (PMID 25955647, 2015). "Thus, our findings of the increased levels of IL‐7, IL‐8, and TNF‐α in patients with prostate cancer are consistent with characteristic features of prostate cancer reported previously." (PMID 26880719, 2016). "The other DEGs with prognostic significance in prostate cancer that were not differentially expressed in our list of DEGs include IL-7, CCL-2, and CDH1." (PMID 26683658, 2015). "The RANKL increment depends at least in part on the increased IL-7 production from T and B cells, but unlike other solid tumors, IL-7 expression is not significantly different in prostate cancer patients and in normal controls." (PMID 23710201, 2013). "It has been shown that high serum IL‐7 levels may help to distinguish patients with prostate cancer from those with benign prostate hypertrophy, unfortunately, it does not seem to be the case in our study, serum IL‐7 could not distinguish MPM from BPE." (PMID 36054746, 2022). "In conclusion, these findings demonstrated that NKG2D is a promising option for CAR T-cell therapy on prostate cancer, and IL-7 has enhanced effect on NKG2D-based CAR T-cell immunotherapy, providing a novel adoptive cell therapy for prostate cancer either alone or in combination with IL-7." (PMID 32698361, 2020). "However, in all the specific cancer groups (NSCLC, prostate cancer and SCLC) we found that patients with bone metastasis had higher IL-7 levels than patients without osteolysis." (PMID 17205128, 2006).
multiple sclerosis (30 papers, 2005 to 2025). A progressive autoimmune disorder affecting the central nervous system resulting in demyelination. "In MS, genetic variations in the IL-7R gene are linked to disease susceptibility, and IL-7 impacts the survival and differentiation of T cell subsets involved in multiple sclerosis pathogenesis." (PMID 40313966, 2025). "We integrated data from across AFGR to further elucidate the potential functionality of this variant, as well as its roles in IL7 regulation and multiple sclerosis risk." (PMID 37986808, 2023). "Its role is essential for the development of both adaptive and innate immunity lymphocytes, while previous reports have associated IL-7 signaling with multiple sclerosis through its effect in the dysregulation of N-glycosylation." (PMID 35277195, 2022). "Serum IL-7 is increased in some age-related diseases, including osteoarthritis and genetic variation in the IL7RA/IL7 pathway increased susceptibility to multiple sclerosis." (PMID 29686666, 2018). "In accordance, high sIL-7R as well as IL-7 plasma concentrations were associated with multiple sclerosis, and sIL-7R had potentiating effects on exacerbation of experimental autoimmune encephalomyelitis." (PMID 28582466, 2017). "For example, IL-7 has been associated with preferential expansion and activation of autoreactive T-cells in multiple sclerosis." (PMID 15642146, 2005). "To highlight the combined utility of data in AFGR, we explored a multiple sclerosis GWAS region that colocalized with African and European meta-analyzed eQTLs associated with IL7 expression, an immune-related gene implicated in multiple sclerosis, as well as multiple caQTLs nearby." (PMID 37986808, 2023). "IL7 itself is a pro-inflammatory cytokine expressed by a wide variety of cells and tissues, it has been shown to have fundamental role in lymphocyte development, has been associated with T1D and multiple sclerosis." (PMID 25933188, 2015). "Additionally, altered expression of the genes encoding IL7Rα and its ligand, IL7, has been found in the cerebrospinal fluid of individuals with multiple sclerosis." (PMID 25393235, 2014). "Currently, a new drug targeting IL-7 is under development for the treatment of multiple sclerosis (ClinicalTrials.gov NCT05131971)." (PMID 40323267, 2025). "Genetic suppression of IL-7 expression in mice led to reduced development of experimental autoimmune encephalomyelitis, a murine model for human multiple sclerosis." (PMID 40323267, 2025). "IL7/IL7R signaling may play a role in various autoimmune or inflammatory diseases including multiple sclerosis, type 1 diabetes mellitus, RA, and ulcerative colitis." (PMID 38401037, 2024). "Interestingly increased IL-7 in the serum has been found in patients with multiple sclerosis, a demyelinating disease of the central nervous system." (PMID 32059364, 2020). "In a multiple sclerosis animal model, hepatocellular IL-7, which was induced by toll-like receptor (TLR) signaling, was described as an important source of IL-7, which enables survival of CD8+ and CD4+ T cells." (PMID 33584648, 2020). "As IL-7 has also been implicated in neuromyelitis optica (NMO), a condition marked by antibodies against aquaporin 4 (AQP-4) water channels, IL-7 may protect not only from PTSD and CVD but also from NMO, and the related condition, multiple sclerosis (MS)." (PMID 37218755, 2023). "In addition, IL-7 signaling is necessary to induce the differentiation of Th1 cells rather than Th17 cells, and serum IL-7 levels correlate inversely with responsiveness to IFN-β therapy in Th1-mediated experimental autoimmune encephalomyelitis (EAE), a mouse model of multiple sclerosis (MS)." (PMID 37373104, 2023).
colitis (27 papers, 2012 to 2025). Inflammation of the colon. "In TCRα−/− mice and T-cell-transfer-induced colitis, high expression of IL-7Rα on T cells is associated with colitis, and IL-7-producing bone marrow cells may harbor colitogenic memory CD4+ T cells." (PMID 23057802, 2012). "Thirdly, the importance of IL-7 as a mediator of intestinal inflammation has been demonstrated in IL-7 transgenic mice which develop colitis resembling ulcerative colitis, and in IL-7 deficient mice, which are resistant to the development of non-T-, non-B-cell-mediated colitis." (PMID 23057802, 2012). "The AHR ligand FICZ ameliorates experimental colitis by lowering the number of activated IELs and reducing IL-7 production." (PMID 37179416, 2023). "Specifically, FICZ, as an endogenous ligand of AHR, reduces epithelial cell-derived IL-7 expression, concomitant with the amelioration of experimental colitis by reducing the frequency of activated IELs." (PMID 37179416, 2023). "Berberine can significantly reduce the levels of pro-inflammatory cytokines (TNF, IFN-γ, KC, IL-7) in colon tissue and improve the symptoms of intestinal injury and colitis model induced by dextran sulfate sodium in mice." (PMID 34594213, 2021). "The secretion of IL-2, IL-7, IL-12, and IL-15 in colonic tissues from colitis mice in the DSS group was higher than that in the normal, DSS + SSP, and DSS + 5-ASA groups." (PMID 32714185, 2020). "Mao and coworkers suggested that, in addition to the inhibition of NF-κB and iNOS, MSC-EVs exert their beneficial effects in colitis through the inhibition of IL-7 signaling in colon macrophages, as well." (PMID 31835680, 2019). "Prompted by this finding, we assessed the functional contribution of these T cells and found that indeed combined blockade of IL-7R/IL-7 interaction and GM-CSF proved to be very effective in harnessing GvHD driven colonic inflammation." (PMID 29910804, 2018). "Two other groups found that the IL-7/IL-7R-dependent signaling pathway is involved in both the immune response in the intestinal mucosa and in the development of colitis." (PMID 29854799, 2018). "We also found that IL-7 expression increased in the colon tissues of colitis patients than that in normal controls, which was similar to the previous studies." (PMID 28589143, 2017). "We found that there was more IL-7+ cells in the colon tissues of colitis patients than that in normal controls." (PMID 28589143, 2017). "In mice, overexpression of IL-7 results in chronic colitis, and T-cell adoptive transfer studies suggest that memory T cells expressing high amounts of IL-7R drive colitis and are maintained and expanded with IL-7." (PMID 23057802, 2012). "Il-7 is an inflammatory cytokine that is upregulated during DSS-induced colitis." (PMID 39337636, 2024). "In short, IL-7 blockade mediates the favorable impacts of AHR pathway activation on colitis." (PMID 37179416, 2023). "Whereas, rCsCP ameliorated the acute colitis might through activating innate immunity, downregulating the expression of pro-inflammatory factors (IL-12, IL-23r and IL-7), and promoting the production of anti-inflammatory factors (IL-10, IL-4 and IL-13)." (PMID 36084127, 2022). "This cytokine was found to contribute to inflammation, because according to a recent mechanistic study, upon downregulating IL-7 in the intra-epithelial lymphocytes of mice with colitis, inflammation could be reduced." (PMID 36555301, 2022). "Inhibit inflammatory cytokine production by colonic macrophages stimulated with LPS and promote the polarization of these macrophages into M2 phenotype in vitro and also, alleviate colitis by inhibiting expression of IL-7 and iNOS in mouse colonic macrophages in vivo." (PMID 35058912, 2021). "The downregulation of IL-7 in mice with DSS-induced colitis could inhibit inflammation in the gastrointestinal tract." (PMID 28589143, 2017).
colitis (continued). "Furthermore, we detected the expression of IL-7 in the colon tissues of normal controls and colitis patients by using immunohistochemistry." (PMID 28589143, 2017). "Furthermore, study showed that exosomes from human umbilical cord mesenchymal stem cells have effects on alleviating DSS-induced colitis through modulating IL-7 expression in macrophages." (PMID 28959207, 2017). "Moreover, we found that the expression of IL-7 was higher in the colon tissues of colitis patients than that of healthy controls." (PMID 28589143, 2017). "Furthermore, we demonstrate that IEC accumulate in the colon of lymphopenic mice in an IL-7/IL-7R-dependent fashion correlating with decreased colitis induction." (PMID 22384106, 2012). "Finally, the importance of IL-7-responsive-T cells in colitis has been demonstrated in TCRα−/− mice, which develop spontaneous colitis driven by IL-7Rhigh memory T cells." (PMID 23057802, 2012). "However, the blockade of the IL-7/IL-7R signaling pathway renders T cell-deficient mice more sensitive to chemically-induced IEC damage and subsequent colitis." (PMID 22384106, 2012). "Importantly, these resident BM CD4+ memory T cells are closely associated with IL-7-producing stromal cells, and they cannot induce colitis when transferred into IL-7−/− × Rag1−/− mice, suggesting that IL-7 plays an essential role in their maintenance or survival in the BM." (PMID 26734007, 2015). "They first elucidated the biological role of m6A modification inthe pathogenesis mediated by T cells, confirming that m6A mRNAdemethylation controls T cell homeostasis by targeting IL-7/STAT5/SOCS pathway, thusinhibiting the occurrence of colitis." (PMID 35675496, 2023). "In conclusion, our findings suggest that exosomes from hucMSCs inhibit the expression of IL-7 in macrophages and relieves inflammatory responses, which attenuates DSS-induced colitis in mice." (PMID 28589143, 2017). "Here we provide evidence that IL-7 regulates IEC homeostasis in the colon and protects lymphopenic mice from DSS-induced colitis." (PMID 22384106, 2012). "Under lymphopenic conditions, elevated levels of IL-7 promote IEC hyperplasia and protect mice from colitis." (PMID 22384106, 2012). "In contrast, IL-7 consumption by T cells prevents IEC hyperplasia and facilitates colitis induction." (PMID 22384106, 2012). "In summary, our results demonstrate that IL-7 protects Rag− mice from DSS-induced tissue damage and subsequent colitis." (PMID 22384106, 2012). "IL-22-producing ILC are important regulators of intestinal homeostasis, they are generated in an IL-7/IL-7R-dependent fashion and protect Rag− mice from DSS-induced colitis." (PMID 22384106, 2012). "In an adoptive transfer model of mouse colitis mimicking human inflammatory bowel disease, IL-7 knockout mice did not develop chronic colitis." (PMID 40323267, 2025). "Analysis of cytokines predicted to activate Ifng expressing CD4+ T cells in CPI colitis included IL2 (z score 4.7, P < 1.0 × 10−27), IL7 (z score 3.8, P < 9.8 × 10−19), IL15 (z score 3.4, P < 5.2 × 10−34), IL18 (z-score 2.0, P < 4.0 × 10−25) and IL23A (z-score 2.6, P < 2.1 × 10−31)." (PMID 37872166, 2023). "In DSS-induced colitis mice, AHR activation downregulates IL-7 and reduces inflammation." (PMID 37179416, 2023). "Exosomes from human umbilical cord MSCs (UCMSCs) inhibited IL-7 expression in peritoneal macrophages, suggesting that exosome treatment may affect IL-7 expression in macrophages and thus attenuate DSS-induced colitis in mice." (PMID 35955628, 2022). "Importantly, IEC hyperplasia and protection from colitis are blocked, if naive CD8+ T cells consume IL-7 or IL-7R signaling is inactive in IEC." (PMID 22384106, 2012). "Dissimilarly, rCsCP ameliorated colitis mainly through stimulating innate immunity, such as Toll like receptor (TLR) signaling pathway, down-regulating the expression of inflammatory cytokines (e.g., IL-12b, IL-23r and IL-7), thereby restraining the differentiation of Th1/Th17 cells." (PMID 36084127, 2022).
colitis (continued). "NKp46+ ILC-specific inactivation of c-FLIP leads to the loss of all IL-7/IL-15-dependent NKp46+ ILC, thereby inducing early-onset chronic colitis and subsequently microbial dysbiosis; meanwhile, the depletion of cNK, but not NKp46+ ILC1/3, aggravates experimental colitis." (PMID 32103006, 2020).